THBS1 (thrombospondin 1)
Diseases named in the same sentence as THBS1 in open-access papers (continued):
Sharing a sentence is not in itself a finding about the gene and the disease.
prostate tumors (5 papers, 2010 to 2024). "Based on previous reports from our lab and others, Kaiso is associated with EMT reprogramming in high-grade breast and prostate tumors, Kaiso may also mediate immune modulation through the downregulation of THBS1 directly and upregulation of CD47 indirectly." (PMID 37190208, 2023). "We used a published proteomic database that includes proteomic profiling of 8 normal prostate tissues as control, 28 localized prostate tumors, and 22 bone metastases and found that the expression of THBS1 was significantly higher than in the control prostate tissue and localized prostate tumors." (PMID 39304722, 2024).
pulmonary fibrosis (5 papers, 2021 to 2025). Chronic progressive interstitial lung disorder characterized by the replacement of the lung tissue by connective tissue, leading to progressive dyspnea, respiratory failure, or right heart failure. "Four aging-associated core genes (Slc2a3, Fga, Hp, and Thbs1) were related to the development of pulmonary fibrosis." (PMID 34746180, 2021). "We also identified four aging-associated core genes (Slc2a3, Fga, Hp, and Thbs1) related to the development of pulmonary fibrosis." (PMID 34746180, 2021). "THBS1 promotes angiogenesis by the HIF-1/VEGF signaling pathway, and it is also associated with cell proliferation and apoptosis; a decrease in THBS1 expression can accelerate cell apoptosis, and an increased rate of cell apoptosis is also one of the causes of pulmonary fibrosis." (PMID 41472112, 2025). "In pulmonary fibrosis, miR-335-3p targets THBS1; overexpression of THBS1 exacerbates TGF-β1-induced epithelial-mesenchymal transition." (PMID 40999501, 2025). "The relationship between Thbs1 and aged pulmonary fibrosis was worth studying." (PMID 34746180, 2021). "Interestingly, thrombospondin-1 deficiency cannot prevent pulmonary fibrosis in the bleomycin-induced model, which suggests that thrombospondin-1 is not essential for TGF-β activation." (PMID 36556326, 2022). "As a performer in pulmonary fibrosis, TGF-β is activated by enzymes such as thrombospondin-1 for the following pro-fibrotic effects." (PMID 36556326, 2022). "The mRNA expression of Itga11, Itgb8, Thbs1, and Thbs2 was significantly upregulated in the o-PF group, indicating the stronger activity of TGF-β in old rats when pulmonary fibrosis occurs." (PMID 36556326, 2022).
acute kidney injury (4 papers, 2022 to 2025). Sudden and sustained deterioration of the kidney function characterized by decreased glomerular filtration rate, increased serum creatinine or oliguria. "Previous studies have demonstrated that THBS1 binds to CD47 to promote acute kidney injury (AKI), and blocking THBS1 signalling by CD47 alleviates renal interstitial fibrosis." (PMID 40977522, 2025).
aortic aneurysm (4 papers, 2016 to 2023). A ruptured aneurysm located in the wall of the proximal portion of the descending aorta proceeding from the arch of the aorta. "DEmiRNAs associated with ruptured aortic aneurysm were identified, of which two could bind to THBS1 and WDR43." (PMID 37122373, 2023). "A direct relationship between THBS1 secretion and increase in inflammation in aortic aneurysm is also noted." (PMID 27635260, 2016).
Arthritis (4 papers, 2012 to 2025). Inflammation of a joint. "Although thrombospondin 4 (THSB4) has not yet been associated with arthritis, thrombospondin 1 (THBS1) is over-expressed in RA tissue." (PMID 23259760, 2012). "Consistently, studies have demonstrated that constitutive expression of thrombospondin 1 (THBS1), a protein involved in FGF signaling pathway, inhibited biomineralization and that THBS1 gene therapy suppressed the progression of arthritis in a rat model of OA." (PMID 23936839, 2013). "We therefore injected into arthritic mice recombinant TGF-β with MMP2, ApoE, C1q, Ttr and Thbs1 but with no success, we did not observed arthritis resolution compared to SuperMApo injection." (PMID 30542342, 2018).
breast invasive carcinoma (4 papers, 2018 to 2024). "Nevertheless, when patients were segregated based upon cancer TNM stage, the levels of THBS1 in stage III was significantly higher than normal samples in TCGA breast invasive carcinoma database (p = 0.041)." (PMID 33912465, 2021). "Consistently, we also found that high expression of THBS1 is associated with the progression of many cancers, including HNSC (head and neck squamous cell carcinoma), BRCA (breast invasive carcinoma), and GBM." (PMID 34804159, 2021). "In our study, we also found that the levels of THBS1 in advance stage were significantly higher than normal samples in TCGA breast invasive carcinoma database." (PMID 33912465, 2021).
breast invasive ductal carcinoma (4 papers, 2009 to 2021). "The role of THBS1 in the maintenance of tumor dormancy of breast invasive ductal carcinoma has been corroborated, pointing to tryptophan as key source for the production of THBS1 by endothelial cells." (PMID 33738282, 2021). "In this study, our data suggested that through thrombospondin 1 (TSP1), tumour-associated microvessel provides a dormant niche to sustain inactive status of breast invasive ductal carcinoma (IDC) cells." (PMID 29156701, 2017). "This study investigates angiogenesis and the expression of thrombospondin 1 in invasive ductal carcinoma of the breast and their possible relation to platelet counts and platelet activity." (PMID 19396698, 2009). "Administration of agents that promote dormancy, such as thrombospondin 1 (TSP1), a glycoprotein secreted from vascular endothelial cells, which has been shown to reduce the proliferation of invasive ductal carcinoma (IDC) cells, may prevent the eventual metastatic outgrowth." (PMID 31817646, 2019).
cardiomyopathy (4 papers, 2017 to 2022). A disease of the heart muscle or myocardium proper. "However, Thbs1 was unique in that it alone caused lethal cardiomyopathy leading us to investigate more deeply into the ER stress response in the Thbs1 and Thbs3 transgenic hearts." (PMID 34168130, 2021). "Here we investigated the role of Thbs1 and observed that Thbs1 heart-specific transgenic mice have dramatically reduced heart size leading to lethal cardiomyopathy by 16 weeks of age." (PMID 34168130, 2021). "Indeed, the mutant form of Thbs1 lacking the type-1 repeat region, which harbors the angiogenesis and TGFβ affecting domains, similarly led to lethal cardiomyopathy due to persistent atrophy." (PMID 34168130, 2021). "Importantly, using doxycycline (Dox) to repress transgene expression and bypass effects during early postnatal development, we showed that adult-specific induction of Thbs1 expression in the heart still led to lethal cardiomyopathy, as none survived past 32 weeks of age." (PMID 34168130, 2021).
Cirrhosis (4 papers, 2023 to 2025). A chronic disorder of the liver in which liver tissue becomes scarred and is partially replaced by regenerative nodules and fibrotic tissue resulting in loss of liver function. "They discovered that extracellular vesicle-specific proteins such as thrombospondin-1, fibulin-1, and fibrinogen gamma chain could distinguish between healthy volunteers and patients with cirrhosis and HCC." (PMID 38541004, 2024). "Biomarkers such as Thrombospondin-1 (TSP-1), Galectin-3 (Gal-3), and Cystatin C (Cys-C) have been studied for their roles in assessing liver fibrosis and predicting cirrhosis progression." (PMID 40417691, 2025).
dry eye (4 papers, 2021 to 2024). "Methods: 30 female mouse knock-out for the thrombospondin 1 gene were randomized (six per group) in untreated mice euthanized at 6 weeks as negative control (C−) or at 12 weeks as the positive control for dry eye (C+)." (PMID 36831152, 2023). "Furthermore, the development of dry eye syndrome (DES), an ophthalmological complication of SS that manifests in the form of corneal nerve fibre lesions, was recently associated with SNPs in Thrombospondin 1 (THBS1)." (PMID 39335717, 2024).
epilepsy (4 papers, 2017 to 2021). A brain disorder characterized by episodes of abnormally increased neuronal discharge resulting in transient episodes of sensory or motor neurological dysfunction, or psychic dysfunction. "Measurement of proteins in serum exosomes from patients with epilepsy revealed that coagulation factor IX (F9) and thrombospondin-1 represent potential new markers for the diagnosis of epilepsy." (PMID 34588957, 2021). "Thrombospondin-1 (THBS1) and DNA topoisomerase 3-beta-1 (TOP3B), proteins reported to be associated with various forms of epilepsy, were also over-represented in SCG patients compared with IE." (PMID 32823271, 2020).
metastatic melanoma (4 papers, 2014 to 2023). A melanoma that has spread from its primary site to another anatomic site. "The results of independence testing analysis showed that genes of CXCL8 and THBS1 had a significant increase of gene expression in metastatic melanoma, but a significant downregulation of KIT expression." (PMID 32894090, 2020).
metastatic tumors (4 papers, 2011 to 2022). "The most notable difference was seen when comparing metastatic vs non-metastatic tumors, where the samples from patients with metastatic tumors had significantly higher expression of THBS1 compared to those from patients with non-metastatic tumors (p = 0.0192, 4.53-fold change)." (PMID 34868914, 2021). "Importantly, some of these genes (THBS1, MAPKAPK2, CD9, TXNIP) were strongly associated with IL-6 signaling, indicating that IL-6 or its associated genes are coupled with metastatic tumors, in alignment with our previous findings." (PMID 34140316, 2021). "We measured DNA methylation for 13 genes in 16 paired primary and liver metastasis specimens which resulted in 205 measurement pairs (Data for THBS1 methylation in one primary and two metastatic tumors was not available)." (PMID 22132162, 2011).
myopia (4 papers, 2022 to 2025). "Among these findings, genes such as ADCY4, a regulator of the cAMP pathway, were functionally linked to high myopia, while THBS1, involved in collagen degradation, was closely associated with the pathophysiology of degenerative myopia." (PMID 40110040, 2025). "Considering the specific role of THBS1 for collagen degradation, its specific contribution on the pathogenesis of myopia can be validated." (PMID 40110040, 2025). "Our findings indicate that sclera THBS1 levels decreased during myopia development and subsequent THBS1 knockdown showed a decrease in scleral COLA1 expression." (PMID 38355399, 2024). "In summary, our study suggests a potential role for THBS1 in mediating scleral ECM remodeling during myopia development." (PMID 38355399, 2024). "In the early stage of myopia induction, THBS1 expression decreased, and this trend continued before day 24 (relatively stable stage of myopia induction)." (PMID 38355399, 2024). "To investigate the potential target gene Thbs1, we utilized lens-induced myopia models in male C57BL/6J mice and performed Western blot analysis to detect the expression level of scleral THBS1 during myopia development." (PMID 38355399, 2024). "The intricate interplay between THBS1, TGF-β1, and MMP9 within the context of scleral remodeling demands more extensive exploration to unravel the mechanisms that underlie myopia development." (PMID 38355399, 2024). "Here, we reported that that lens-induced mouse myopia (LIM) induced the downregulation of scleral THBS1, thereby confirming its potential role in mediating scleral ECM remodeling and ocular axial elongation in mice." (PMID 38355399, 2024). "During lens-induced myopia, THBS1 protein expression in the sclera was downregulated, particularly in the early stages of myopia induction." (PMID 38355399, 2024). "Our in vivo studies demonstrated downregulation of THBS1 expression levels in the sclera of lens-induced myopia during myopia progression, consistent with previous reports in other animal models." (PMID 38355399, 2024). "Previous studies have demonstrated a decreased expression of THBS1 during the development of myopia in a lens-induced myopia model, suggesting its involvement in scleral ECM remodeling." (PMID 38355399, 2024). "Additionally, we evaluated the effects of scleral THBS1 knockdown on myopia development through AAV sub-Tenon’s injection." (PMID 38355399, 2024). "Notably, the decreased expression of scleral THBS1 is observed at the onset of lens-induced myopia (LIM) induction." (PMID 38355399, 2024). "Moreover, the mice in the THBS1 knockdown group exhibited alterations in myopia development in both refraction and axial length changed compared to the control group." (PMID 38355399, 2024). "Taken together, these results suggest that THBS1 plays a role in maintaining the homeostasis of scleral extracellular matrix, and the reduction of THBS1 may promote the remodeling process and then affect ocular axial elongation during myopia progression." (PMID 38355399, 2024). "THBS1 is a known activator of TGF-β1 in vivo and TGF-β1 pathway has been determined as one of the most important pathways during myopia development." (PMID 38355399, 2024). "However, the specific role of THBS1 in myopia development remains unclear." (PMID 38355399, 2024). "Future work should include the evaluation of latent versus active TGF-β pools, as well as endogenous activators such as MMP2, integrins (e.g., αvβ6), or thrombospondin-1, to more precisely model the endogenous regulation of TGF-β activity in the progression of myopia." (PMID 40862775, 2025).
nasopharyngeal carcinoma (4 papers, 2022 to 2024). A carcinoma arising from the nasopharyngeal epithelium. "After knocking down THBS1 in laryngeal cancer and nasopharyngeal cancer, CCK8 detected that the proliferation activity of laryngeal cancer cells was significantly downregulated." (PMID 37686118, 2023).
osteoporosis (4 papers, 2021 to 2024). A condition of reduced bone mass, with decreased cortical thickness and a decrease in the number and size of the trabeculae of cancellous bone (but normal chemical composition), resulting in increased fracture incidence. "The M5 hub gene Thbs1 affects epithelial-to-mesenchymal transition and osteoporosis." (PMID 33631431, 2021). "After construction the miRNA-gene interaction network, we identified 6 hub miRNAs (hsa-miR-18b-3p, hsa-miR-361-3p, hsa-miR-484, hsa-miR-519e-5p, hsa-miR-940, and hsa-miR-1275) and 6 hub genes (THBS1, IFNAR2, ARHGAP5, TUBB2B, FLNC, and NTF3) for osteoporosis." (PMID 35757478, 2022).
preeclampsia (4 papers, 2020 to 2025). Preeclampsia is a hypertensive disorder of pregnancy that is characterized by new-onset hypertension with proteinuria presenting after 20 weeks of gestation, and depending on mild or severe forms may initially present with severe headache, visual disturbances, and hyperreflexia. "On the other hand, THBS1, which is closely involved in endothelial adhesion, motility and proliferation, is significantly downregulated by HtrA4, consistent with THBS1 being lower in women with severe preeclampsia." (PMID 34639128, 2021). "Thrombospondin-1 is expressed in the placenta and has previously been reported in cases of small for gestational age (SGA) pregnancies and preeclampsia." (PMID 33026626, 2020).
rheumatoid arthritis (4 papers, 2012 to 2024). A chronic, systemic autoimmune disorder characterized by inflammation in the synovial membranes and articular surfaces. "In rheumatoid arthritis patients, altered expression levels and tissue distribution of THBS1 was observed." (PMID 29238343, 2017). "Another study also found that THBS1 was significantly down-regulated in OA compared to rheumatoid arthritis." (PMID 22828367, 2012). "It seems that THBS1 might be a biomarker for distinguishing OA from KBD and rheumatoid arthritis." (PMID 22828367, 2012).
skin cancer (4 papers, 2014 to 2026). "This review systematically explores the molecular mechanisms of THBS1 signaling in the skin, highlighting its implications in wound healing, tissue regeneration, inflammatory responses, fibrosis, and skin tumor development." (PMID 41930128, 2026). "Similarly, THBS1, SDC4, and TLN1 have been linked to the development of metastasis and chemoresistance in skin cancer." (PMID 37510272, 2023). "Although the current study focuses on wound repair, the RT-induced epigenetic alteration of the THBS1 gene may also contribute to other late-onset adverse effects of RT, such as fibrosis and secondary skin tumors, highlighting the need for further investigation." (PMID 39468077, 2024).
squamous cell carcinoma (4 papers, 2016 to 2025). A carcinoma arising from squamous epithelial cells. "The findings suggest that downregulation of MCM7, MAPT, TGFB2, and THBS1 by MS13 may inhibit cell proliferation and growth as well as metastasis and invasion in squamous cell carcinoma and adenocarcinoma NSCLC cells." (PMID 34299042, 2021). "Similarly, PERK inhibition markedly suppresses tumor growth and angiogenesis in an orthotopic squamous cell carcinoma model by reducing the expression of FGF2, VEGF, and IL‐6, while increasing the levels of antiangiogenic cytokines/chemokines such as thrombospondin 1 (THBS1), CXCL14, and CXCL10." (PMID 40547943, 2025).
tuberculosis (4 papers, 2012 to 2025). A chronic, recurrent infection caused by the bacterium Mycobacterium tuberculosis. "The discovery of these six mRNAs (NEDD4, PLTP, RNASEL, SEMA7A, TAPBP, and THBS1) not only reveals critical molecular mechanisms underlying immune regulation in tuberculosis but also establishes a robust theoretical foundation for advancing diagnostic and therapeutic strategies." (PMID 40182927, 2025). "NEDD4, PLTP, RNASEL, SEMA7A, TAPBP, and THBS1 were combined into a 6-mRNA feature panel for diagnosis of tuberculosis." (PMID 40182927, 2025). "In our study using whole blood samples from tuberculosis patients, we found that THBS1 expression was downregulated." (PMID 40182927, 2025). "Regarding tuberculosis, spatial transcriptomics has enabled a detailed understanding of granuloma composition, spatial immune dynamics, and fibrosis-related gene expression, offering new insights into disease pathogenesis and potential therapeutic targets such as thrombospondin-1 (THBS1)." (PMID 40563563, 2025). "The results showed that PLTP, RNASEL, SEMA7A, and TAPBP were upregulated in the whole blood of tuberculosis patients, while NEDD4 and THBS1 were downregulated." (PMID 40182927, 2025). "In addition, we propose CD14, IL-1R, THBS1, MMP9 and FYVE as potential biomarkers of bovine tuberculosis." (PMID 22815916, 2012). "In tuberculosis (TB), M. tuberculosis infection activates TGF-β signaling through the upregulation of THBS1/2 and CD36." (PMID 40563563, 2025). "The THBS signaling pathway is widely present in the region enriched with macrophages in the tuberculosis spot, indicating that macrophages and fibroblasts interact depending on THBS1/2-CD36/SDC4/ITGA3/ITGB1, which may be a key pathway for tuberculosis progression." (PMID 39431015, 2024).
vasculitis (4 papers, 2018 to 2025). "Thrombospondin-1 inhibits the complement cascade independently of factor H, revealing a significant role in vasculitis pathomechanisms and potential therapeutic implications." (PMID 40338657, 2025). "Indeed, several miRNAs targeted DEGs associated with blood coagulation (i.e., THBS1, F5, and LMAN1), a process whose alteration is typically associated with BD vasculitis." (PMID 29854829, 2018).